SERPINI1 (serpin family I member 1)
Description:
Serine protease inhibitor that inhibits plasminogen activators and plasmin but not thrombin. May be involved in the formation or reorganization of synaptic connections as well as for synaptic plasticity in the adult nervous system. May protect neurons from cell damage by tissue-type plasminogen activator (Probable).
Synonyms: PI12; HNS-S1; HNS-S2; neuroserpin
Tractability: Antibody: UniProt places it where antibodies can reach, with high confidence; UniProt predicts a signal peptide or a membrane-spanning region; its Gene Ontology location is reachable by antibodies, with medium confidence.
Gene: Protein-coding gene on chromosome 3 (167,735,068 to 167,825,573, forward strand). Ensembl gene ENSG00000163536.
Subcellular location: Secreted; Cytoplasmic vesicle, secretory vesicle lumen; Perikaryon
Subcellular location (Human Protein Atlas): Cytosol; Predicted to be secreted
Gene Ontology:
Molecular function: serine-type endopeptidase inhibitor activity
Biological process: central nervous system development; peripheral nervous system development; positive regulation of neuron projection development
Cellular component: cytoplasmic vesicle lumen; extracellular exosome; extracellular region; neuronal cell body; perikaryon; cytoplasmic vesicle; secretory granule lumen
Genetic constraint (gnomAD): Loss-of-function variants: 6 observed, 25.81 expected, observed/expected ratio (o/e) 0.23, 90% interval 0.13 to 0.46. The upper end of that interval is the gene's LOEUF score, 0.46, which puts it in group 2 of 6, group 1 being the genes least tolerant of losing a copy. Missense variants: 330 observed, 353.24 expected, observed/expected ratio (o/e) 0.93, 90% interval 0.85 to 1.02. Synonymous variants: 106 observed, 120.42 expected, observed/expected ratio (o/e) 0.88, 90% interval 0.75 to 1.03.
Gene-disease validity (ClinGen):
ClinGen rates the evidence that SERPINI1 causes each of these diseases.
progressive myoclonus epilepsy (autosomal dominant): Definitive. A rare group of disorders characterized by the development of myoclonic and tonic-clonic epileptic seizures associated with progressive degeneration of the nervous system.
Homologues: Orthologues: chimpanzee SERPINI1 (99% identical), macaque SERPINI1 (98% identical), dog SERPINI1 (93% identical), rabbit SERPINI1 (91% identical), guinea pig SERPINI1 (90% identical), rat Serpini1 (88% identical), mouse Serpini1 (86% identical), pig SERPINI1 (85% identical), tropical clawed frog serpini1 (71% identical), zebrafish serpini1 (59% identical). Paralogues in human: SERPINI2 (38% identical), SERPINB1 (32% identical), SERPINB3 (32% identical), SERPINB4 (31% identical), SERPINC1 (31% identical), SERPINB6 (31% identical), SERPINB11 (31% identical), SERPINE2 (30% identical), SERPINB13 (30% identical), SERPINB8 (30% identical), SERPINB9 (30% identical), SERPINB12 (29% identical), and 24 more.
Diseases named in the same sentence as SERPINI1 in open-access papers:
SERPINI1 is named in the same sentence as 51 diseases in open-access papers, as found by Europe PMC text mining. Sharing a sentence is not in itself a finding about the gene and the disease. The quoted sentences say what the papers report.
glioma (4 papers, 2021 to 2025). A benign or malignant brain and spinal cord tumor that arises from glial cells (astrocytes, oligodendrocytes, ependymal cells). "In the nervous system, a study based on the analysis of single nucleotide polymorphisms (SNPs) in gliomas proposed a role for the SERPINI1 gene, which appeared to be associated with glioblastoma, the most aggressive type of glioma." (PMID 34405255, 2021). "As predicted, glioma patients with lower SERPINI1/CAMK2A expression were less likely to benefit from immune checkpoint therapy than patients with higher SERPINI1/CAMK2A expression." (PMID 37706017, 2023). "Our study revealed that sevoflurane can more effectively prevent the development of glioma after surgery than propofol, and SERPINI1 can be used as a new independent prognostic factor for glioma." (PMID 37706017, 2023). "In contrast, we found that SERPINI1 could act as an independent prognostic factor for gliomas and was suppressed by propofol." (PMID 37706017, 2023). "Three independent predictors of mortality from the analyses (SERPINI1 expression, age, and tumor grade) were combined to create a prognostic nomogram that was then tested and validated using TCGA data to better predict the prognosis of glioma patients in the clinic." (PMID 37706017, 2023). "Simultaneously, SERPINI1 and CAMK2A were also significantly related to the prognosis of GBM and lower‐grade glioma patients and acted as potential tumor suppressors." (PMID 37706017, 2023). "SERPINI1 and CAMK2A were found to be the only two overlapping genes in both groups, indicating that these genes are not only highly correlated with the progression of glioma but also act as important molecular markers during glioma anesthesia." (PMID 37706017, 2023).
familial encephalopathy with neuroserpin inclusion bodies (3 papers, 2023 to 2025). A neurodegenerative disease that is characterized by intraneuronal inclusions of mutant neuroserpin resulting in progressive encephalopathy, dementia and seizures and has material basis in a mutation in the SERPINI1 gene inherited in an in autosomal dominant pattern. "Mutations of the SERPINI1 gene encoding neuroserpin are associated with the development of familial encephalopathy with neuroserpin inclusion bodies (FENIB), which is often characterized by progressive myoclonic epilepsy." (PMID 41303379, 2025). "For neuroserpin (SERPINI1), polymer formation in the central nervous system is the basis for a hereditary dementia termed Familial Encephalopathy with Neuroserpin Inclusion Bodies (FENIB)." (PMID 37759793, 2023).
hepatocellular carcinoma (3 papers, 2016 to 2021). A malignant tumor that arises from hepatocytes. "In this regard, SERPINI1 is of special interest, as it was found to be a biomarker for hepatocellular carcinoma, and expression of SERPINI1 has been shown to be regulated by c-Myc." (PMID 27385100, 2016).
Parkinson disease (3 papers, 2007 to 2021). A progressive degenerative disorder of the central nervous system characterized by loss of dopamine producing neurons in the substantia nigra and the presence of Lewy bodies in the substantia nigra and locus coeruleus. "Whether or not HFD-induced intestinal tuft cell expression of Serpini1 may play a part in HFD-induced depression or other neurodegenerative disorders like Parkinson’s disease, Alzheimer’s disease, multiple sclerosis, and amyotrophic lateral sclerosis will need further investigations." (PMID 34122403, 2021).
colorectal cancer (2 papers, 2021). A primary or metastatic malignant neoplasm that affects the colon or rectum. "Serpini1 has also been described as a tumor suppressor in gastric tumors as well as having a putative role in epithelial-mesenchymal transition in colorectal cancer models." (PMID 33542375, 2021).
dementia (2 papers, 2007 to 2021). Loss of intellectual abilities interfering with an individual's social and occupational functions. "Though rapidly progressive dementia and myoclonus belong to the clinical spectrum of SERPINI1 mutations, the Ala280Thr variant found in patient 6 is predicted as tolerated by in silico analyses." (PMID 33006056, 2021). "Moreover, thanks to NGS approach, we disclosed other variants in dementia-related genes, in particular FUS, ABCA7, CSF1R, DCTN1, SERPINI1 and SORL1." (PMID 33006056, 2021). "Furthermore, the genetic mutations of SERPINI1 and PARK2 are able to accelerate the formation of cellular inclusion bodies and to cause the dementia symptom." (PMID 17212813, 2007).
Obesity (2 papers, 2019 to 2021). Accumulation of substantial excess body fat. "By comparing regulators that were identified for lean, obese, and merged islet expression data, Cck, C1ql3, Serpina7, Creld2, Svop, Smoc1, Tgfβ3, and Serpini1 were identified to affect islet function in obesity." (PMID 31300714, 2019). "Moreover, identification of small intestinal tuft cell-derived Serpini1 as an early marker of HFD intake and obesity development points to the involvement of a direct tuft cell-neuro circuit in diet-induced obesity." (PMID 34122403, 2021).
schizophrenia (2 papers, 2009 to 2016). A major psychotic disorder characterized by abnormalities in the perception or expression of reality. "Seven genes, APP, ERBB3, FEZ1, HSPA2, SERPINI1, SOX10 and SYN2, display altered expression in studies of schizophrenia or bipolar disorder." (PMID 19300510, 2009).
Anxiety (1 paper, 2018). Intense feelings of nervousness, tension, or panic often arise in response to interpersonal stresses. "Additionally, mice with dysregulated expression of SERPINI1 show selective reduction of locomotor activity in novel environments, anxiety-like responses, and neophobic response to novel objects." (PMID 29995933, 2018).
brain tumors (1 paper, 2007). "In addition to the mutations at the DNA level, the mRNA expression of SERPINI1 was found to be down-regulated or lost in brain tumors." (PMID 17212813, 2007). "While SERPINI1 is predominantly expressed in normal brain and down-regulated in brain tumors, PDCD10 is ubiquitously expressed in all normal tissues but its gene transcription becomes aberrant in different types of cancers." (PMID 17212813, 2007). "In this study, we present evidence showing that while SERPINI1 is predominantly expressed in brain and down-regulated in brain tumors, PDCD10 is ubiquitously expressed in all normal tissues but its gene transcription becomes aberrant in different types of cancers." (PMID 17212813, 2007). "Results from the semi-quantitative RT-PCR indicate that while SERPINI1 expression was negatively correlated with tumor progression, the mRNA level of PDCD10 was not much affected in brain tumor cells." (PMID 17212813, 2007).
colorectal tumour (1 paper, 2021). "A role for neuroserpin in promoting epithelial-mesenchymal transition in colorectal tumour cells has also been suggested, based on microarray analysis of cell lines and the effects of siRNA knock-down of SERPINI1 gene in one of the cell lines." (PMID 34405255, 2021).
Creutzfeldt-Jakob disease (1 paper, 2024). "In a study based on analyzing human SERPIN transcripts, SERPINI1 was significantly downregulated in Sporadic Creutzfeldt-Jakob disease patients." (PMID 38626069, 2024).
glaucoma (1 paper, 2021). Increased pressure in the eyeball due to obstruction of the outflow of aqueous humor. "Interestingly, neuroserpin encoded by SERPINI1, primarily expressed in neuronal cells, was down-regulated in the AH of glaucoma patients, analyzed by mass spectrometry." (PMID 34943212, 2021).
kidney stones (1 paper, 2024). "In this context, variations in the expression profile of miRNAs (e.g., miR-7b-3p, miR-22-3p, miR-127-3p, miR-181a-5p, miR-214-5p, and miR-223-3p) and lncRNAs (lnc-EVI5L-1, lnc-FAM72B-4, lnc-KIN-1, lnc-MB-6, lnc-SERPINI1–2, and lnc-TIGD1L2–3) have been found to be associated with kidney stones." (PMID 38275604, 2024).
metastasis (1 paper, 2021). The spread or migration of cancer cells from one part of the body (where they first appeared) to another. "Also, in a whole-exome sequencing study, SERPINI1 has been found as the most frequently mutated gene in brain metastasis, adding further evidence for a role of neuroserpin in this process." (PMID 34405255, 2021).
neuroblastoma (1 paper, 2016). Neuroblastoma (NB) is the most common solid, extracranial childhood tumor. "To determine if miR-27a has the ability to increase Serpini1 protein levels, we transfected two cell lines, mouse N2A and N1E-115 neuroblastoma cells, with a miR-27a mimic and measured protein levels of Serpini1." (PMID 27047334, 2016).
prion disease (1 paper, 2022). A transmissible disease that is caused by a protein that is able to induce abnormal folding of normal cellular proteins, leading to characteristic spongiform brain changes, which are associated with neuronal loss without an inflammatory response. "Our analysis revealed that, besides the already observed upregulation of SERPINA3 in patients with prion disease and AD, SERPINB1, SERPINB6, SERPING1, SERPINH1, and SERPINI1 were dysregulated in sCJD individuals compared to controls, while only SERPINB1 was upregulated in AD patients." (PMID 35416570, 2022).
cancer (10 papers, 2007 to 2023). A tumor composed of atypical neoplastic, often pleomorphic cells that invade other tissues. "Cumulative evidence from genetic studies has revealed the existence of a cancer-related gene cluster at the SERPINI1 locus that codes for neuroserpin, at the 3q26 chromosomal band." (PMID 35244780, 2022). "These included several candidate tumor suppressor genes, such as ABLIM1, CYFIP2, VPS13A, SERPINI1, TET2, HTRA4, UBE2L6, as well as oncogenes/genes implicated as biomarkers in other cancers, such as FAM65B and TCF7L2." (PMID 27385100, 2016). "These abnormalities, along with our latest findings that its adjacent gene SERPINI2 is also down-regulated in cancer, prompted us to study the regulatory mechanism of SERPINI1 gene in both normal and cancerous brain tissues." (PMID 17212813, 2007). "Besides, SERPINI1 gene has been reported to be involved in malignant tumors." (PMID 34852762, 2021). "To verify the role of SERPINI1 and CAMK2A, we first evaluated the expression of SERPINI1 and CAMK2A in TCGA‐LGG (Grade2 & Grade3), GBM and para‐cancer." (PMID 37706017, 2023). "For example, SERPINI1, NOTUM and FGFR1 have some related to the cancer biomarker." (PMID 34852762, 2021). "In gastric cancer, a screening for targets of the oncogenic microRNA miR-21 identified SERPINI1 as a target gene, and neuroserpin overexpression induced G1/S arrest and decreased the growth of MKN28 cells, suggesting a potential tumour suppressive function in this type of cancer." (PMID 34405255, 2021).
tumor (10 papers, 2007 to 2025). "The frequency of gene mutations of the pathway was significantly higher in BMs than in primary tumours, and SERPINI1 was the most frequently mutated gene in BMs." (PMID 28747664, 2017). "A recent study of methylated gene profiles in bladder cancer has revealed that the SERPINI1 gene is differentially methylated when comparing tumour and normal tissues." (PMID 34405255, 2021). "The results indicated that SERPINI1 and CAMK2A were negatively correlated with tumor proliferation in LGG and GBM." (PMID 37706017, 2023). "The lncRNA PVT1 and predicted target SERPINI1 (serpin peptidase inhibitor-clade I (neuroserpin)-member 1) were upregulated in OvCa cell lines and tumor tissues, unlike the downregulated tumor-suppressive miR-543." (PMID 33238475, 2020). "Moreover, as SERPINI1 and SERPINI2 were both reported to be down-regulated during tumor development, it is rational to doubt that the expression of PDCD10, which is located in between the two SERPINI genes at chromosome 3q26, may also be altered in some tumors." (PMID 17212813, 2007).
neurodegenerative disease (5 papers, 2021 to 2025). A disorder of the central nervous system characterized by gradual and progressive loss of neural tissue and neurologic function. "One type of neurodegenerative disease is FENIB, of which the etiology is associated to mutations in the SERPINI1 gene causing the encoded NS proteins to have a higher tendency to polymerize and to be retained in the ER." (PMID 34361933, 2021). "Therefore, the role of SERPINI1 could be further investigated in other neurodegenerative diseases like PD targeting α-synuclein and ER homeostasis." (PMID 38626069, 2024).
brain diseases (2 papers, 2007 to 2009). "Here we present evidence that two non-homologous brain diseases-related genes, SERPINI1 and PDCD10, are tightly linked in a divergent configuration by a bidirectional promoter in an evolutionarily conserved fashion." (PMID 17212813, 2007). "Besides, there are evidences indicating that PDCD10 and SERPINI1 are both related to brain diseases." (PMID 17212813, 2007).
adrenal gland (1 paper, 2007). "The rat adrenal gland pheochromocytoma PC-12 cell line was also used for comparison as it had previously been chosen for the study of mouse Serpini1 promoter." (PMID 17212813, 2007).
infection (1 paper, 2012). The state of being infected such as from the introduction of a foreign agent such as serum, vaccine, antigenic substance or organism. "At 24 h post-infection, knockdown of TNFRSF9 and SERPINI1 reversed the ability of IFN-γ to restrict survival of F. tularensis SchuS4 in THP-1 cells, as shown by CFU assay." (PMID 22359626, 2012). "Then we evaluated virulent F. tularensis SchuS4 infection of THP-1 cells in which six top hit genes (TNFRSF9, SERPINI1, HLA-DBR1, PLEK2, ATG5 and ATG16L1) were knocked down by individual lentiviral shRNA." (PMID 22359626, 2012).
SERPINI1 also shares sentences with these, for which no sentence is quoted: angioedema (2 papers); gastric cancer (2); neurological disorders (2); Alzheimer disease (1); amyotrophic lateral sclerosis (1); bipolar disorder (1); cerebral cavernous malformation (1); cognitive decline (1); depression (1); emphysema (1); Encephalopathy (1); epilepsy (1); gastric tumors (1); genetic disorder (1); hepatoblastoma (1); hereditary dementia (1); hyperkalemic periodic paralysis (1); Lafora disease (1); Listeria monocytogenes infection (1); lung adenocarcinoma (1); lung carcinoma (1); mental retardation (1); mental retardation, X-linked 21 (1); multiple sclerosis (1); myoclonic epilepsy (1); Myoclonus (1); pancreatic cancer (1); Parkinsonism (1).